PPIC (peptidylprolyl isomerase C)
Description:
PPIase that catalyzes the cis-trans isomerization of proline imidic peptide bonds in oligopeptides and may therefore assist protein folding.
Synonyms: CYPC
Tractability: PROTAC: ubiquitination databases record sites on it; its protein half-life has been measured; a small molecule that binds it is known.
Target class: Isomerase; Enzyme
Gene: Protein-coding gene on chromosome 5 (123,022,052 to 123,036,725, reverse strand). Ensembl gene ENSG00000168938.
Subcellular location: Cytoplasm
Gene Ontology:
Molecular function: peptidyl-prolyl cis-trans isomerase activity; protein binding; cyclosporin A binding
Biological process: protein folding
Cellular component: extracellular exosome; cytoplasm
Genetic constraint (gnomAD): Loss-of-function variants: 17 observed, 18.82 expected, observed/expected ratio (o/e) 0.9, 90% interval 0.62 to 1.35. The upper end of that interval is the gene's LOEUF score, 1.35, which puts it in group 5 of 6, group 1 being the genes least tolerant of losing a copy. Missense variants: 265 observed, 266.99 expected, observed/expected ratio (o/e) 0.99, 90% interval 0.9 to 1.1. Synonymous variants: 107 observed, 100.4 expected, observed/expected ratio (o/e) 1.07, 90% interval 0.91 to 1.25.
Homologues: Orthologues: chimpanzee PPIC (98% identical), macaque PPIC (97% identical), pig PPIC (92% identical), dog PPIC (92% identical), mouse Ppic (91% identical), guinea pig PPIC (90% identical), rabbit PPIC (82% identical), tropical clawed frog ppic (74% identical), zebrafish PPIC (65% identical), rat Ppic (56% identical), Caenorhabditis elegans cyn-9 (40% identical), Drosophila melanogaster Cyp40 (38% identical). Paralogues in human: PPIB (64% identical), PPID (46% identical), PPIF (46% identical), PPIA (44% identical), PPIH (44% identical), NKTR (42% identical), PPIE (42% identical), PPIG (42% identical), PPIAL4C (42% identical), PPIAL4A (41% identical), PPIAL4D (41% identical), PPIAL4E (41% identical), and 10 more.
Diseases named in the same sentence as PPIC in open-access papers:
PPIC is named in the same sentence as 22 diseases in open-access papers, as found by Europe PMC text mining. Sharing a sentence is not in itself a finding about the gene and the disease. The quoted sentences say what the papers report.
ovarian carcinoma (6 papers, 2011 to 2024). A malignant neoplasm originating from the surface ovarian epithelium. "The prognostic potential of PPIC was shown in high-grade glioma and in ovarian cancer PPIC was co-expressed with a gene signature associated with periostin, a gene product with reported roles in metastasis and angiogenesis." (PMID 34073412, 2021). "We found that among the selected ovarian-cancer-specific transcripts, only the presence of PPIC mRNA in the enriched blood samples was associated with worse overall (OS) and progression-free survival (PFS)." (PMID 34073412, 2021). "In our earlier RT-qPCR-based studies we identified a 6-gene panel for the detection of CTCs in breast cancer and gynecological malignancies, and a further panel (comprising the cyclophilin C encoding gene PPIC) specifically for ovarian cancer." (PMID 29416657, 2018). "In the ovarian cancer samples, PPIC was the most prominent gene marker, contributing to all positive cases and at least to 70% of the positive cases after pre-amplification of the respective target genes." (PMID 29416657, 2018). "A study has also verified that patients with platinum resistance are more prone to having Cyclophilin C gene (PPIC) positive CTCs, which may suggest unfavourable outcomes for ovarian cancer." (PMID 39492906, 2024). "A panel of six genes: CCNE2, DKFZp1312, PPIC, EMP2, MAL2 and SLC6A8 may serve as potential markers for CTC derived from breast, endometrial, cervical, and ovarian cancers." (PMID 21827674, 2011).
breast carcinoma (5 papers, 2010 to 2024). "The markers SCGB2A2, EpCAM, SLC6A8 and PPIC were detectable in about half of the metastatic breast cancer samples." (PMID 36831613, 2023). "Indeed, EMP2 and PPIC transcripts in spiked blood samples indicated the presence of Hs579T breast cancer cells; in contrast, the analysis of the epithelial markers EpCAM, CK19 and SCGB2A2 alone would not have detected these hormone receptor and HER2-negative cells." (PMID 36831613, 2023). "In a recent study, using RT-qPCR, two panels of transcripts related to the presence of CTCs (Panel 1: CK19, EpCAM, SCGB2A2 and Panel 2: EMP2, SLC6A8, HJURP, MAL2, PPIC and CCNE2), in two cohorts of breast cancer patients (metastatic and early), were evaluated." (PMID 37046848, 2023). "A panel of six genes: CCNE2, DKFZp762E1312, EMP2, MAL2, PPIC, and SLC6A8 that were over-expressed in the blood of 81% of patients with recurrent breast cancer was then chosen as gene markers for the molecular detection of CTC." (PMID 21129172, 2010). "In our present study, we evaluated two panels of transcripts related with the presence of circulating tumor cells (CTCs) (Panel 1: CK19, EpCAM, SCGB2A2 and Panel 2: EMP2, SLC6A8, HJURP, MAL2, PPIC and CCNE2) in two cohorts of breast cancer patients (metastatic and early)." (PMID 36831613, 2023). "We have shown that the RT-qPCR-based multi-marker analysis using the six genes: CCNE2, DKFZp762E1312, EMP2, MAL2, PPIC, or SLC6A8 more than doubled the number of positive patients with recurrent breast cancer compared to the analysis of hMAM or EpCAM gene expression alone." (PMID 21129172, 2010).
glioma (3 papers, 2016 to 2021). A benign or malignant brain and spinal cord tumor that arises from glial cells (astrocytes, oligodendrocytes, ependymal cells). "We analyzed expression of PPIC, EMP3 and CHI3L1 in expression profiles acquired from the Gene Expression Omnibus (GEO) database, and glioma datasets acquired from The Cancer Genome Atlas (TCGA)." (PMID 27801851, 2016). "The other well-predicted genes, including COL5A1, CPA4, CSTB, and PPIC in gliomas and DAK, ITPRIP, TM4SF19, TMEM200A in RCC have not been studied thoroughly in cancer and their roles in cancer worth further investigating." (PMID 32194984, 2020). "Intersection of the DEPGs revealed a total of three common DEPGs—PPIC, EMP3 and CHI3L1—suggesting that these common DEPGs may be potential prognostic indicators of glioma progression." (PMID 27801851, 2016). "We determined that PPIC, EMP3 and CHI3L1 were up-regulated in the glioma tissue." (PMID 27801851, 2016). "After intersecting DEPGs generated from the two datasets, three common DEPGs (PPIC, EMP3 and CHI3L1) were identified, suggesting that these genes may be potential predictors of prognosis in high-grade gliomas patients." (PMID 27801851, 2016). "Taken together, the results suggest that expressions of PPIC, EMP3 and CHI3L1 may play a vital role in glioma progression." (PMID 27801851, 2016). "Therefore, we propose that PPIC, EMP3 and CHI3L1 may be suitable as prognostic genes or therapeutic targets for high grade gliomas." (PMID 27801851, 2016).
adenoma (1 paper, 2024). A neoplasm arising from the epithelium. "Most over-represented proteins in the adenoma cell line ZMTH3 were associated with RNA-binding and protein expression (EIF1AX, CSRP1, PPIC), suggesting enhanced protein biosynthesis activity." (PMID 39462388, 2024).
gastric cancer (1 paper, 2013). A primary or metastatic malignant neoplasm involving the stomach. "We demonstrated that PPIC is one of the target genes of miR-29c and was significantly upregulated in gastric cancer tissues." (PMID 23442884, 2013). "RCC2 and PPIC were actually upregulated in gastric carcinoma tissues, and therefore both were identified as possible targets of miR-29c in gastric carcinoma." (PMID 23442884, 2013). "To clarify this issue, we analyzed the expression levels of RCC2, PPIC and CDK6 mRNAs in gastric carcinoma tissues and normal epithelial tissues using quantitative RT-PCR." (PMID 23442884, 2013). "This suggests that RCC2 and PPIC may be the target of miR-29c in gastric carcinoma, whereas CDK6 may not." (PMID 23442884, 2013).
lung neoplasm (1 paper, 2017). A benign or malignant, primary or metastatic neoplasm involving the lungs. "PPIC gene was associated with endometrial, kidney, and lung neoplasms." (PMID 28812028, 2017).
malignant glioma (1 paper, 2016). A grade III or grade IV glioma arising from the central nervous system. "Analysis of the GSE7696 data revealed that PPIC, EMP3 and CHI3L1 have greater than two-fold up-regulation at the transcription level and were drastically increased in malignant gliomas when compared to non-tumor brain tissue." (PMID 27801851, 2016).
melanoma (1 paper, 2016). A malignant, usually aggressive tumor composed of atypical, neoplastic melanocytes. "We examined LAMC1 and PPIC in detail as potential mediators of miR-29b-3p effects across our melanoma cell models." (PMID 27852308, 2016).
cancer (9 papers, 2013 to 2026). A tumor composed of atypical neoplastic, often pleomorphic cells that invade other tissues. "The detection of as few as 10 SKBR3 cancer cells isolated from a peripheral blood matrix (5 mL) was possible using the markers CK19, SCGB2A2, EpCAM, EMP2, MAL2 and PPIC." (PMID 36831613, 2023). "In the next step, we processed blood samples from 36 cancer patients and 12 healthy donors (cohort 1) using protocol A and measured the gene expression levels of EpCAM, MAL2, PPIC, and TUSC3 in the enriched cell fractions." (PMID 29416657, 2018). "The expression levels of RCC2 and PPIC were actually upregulated in carcinoma tissues relative to normal tissues, whereas CDK6 was not." (PMID 23442884, 2013). "A panel of six genes (CCNE2, DKFZp762E1312, EMP2, MAL2, PPIC and SLC6A8) were over-expressed in cancer cell lines and were absent in healthy women." (PMID 29132396, 2017).
tumor (4 papers, 2010 to 2023). "In that approach, we analyzed the expression levels of 11 genes, among them the cyclophilin C (PPIC) encoding gene, which had been selected upon a whole transcriptome analysis of patient tumor tissue and control blood samples." (PMID 34073412, 2021). "Low PPIC protein expression was found in 19 (11.9%) of the cases, medium levels in 63 (39.4%), high levels in 45 (28.1%), and very high levels in 33 (20.6%) of the tumor tissues." (PMID 34073412, 2021).
infection (2 papers, 2019 to 2024). The state of being infected such as from the introduction of a foreign agent such as serum, vaccine, antigenic substance or organism. "The clearance rates from enterococcal bacteremia following immunization with PpiC, GelE, and VS87_01105 recombinant proteins were within 96 h after the challenge, although mice immunized with PpiC have been cleared at 48 h after infection." (PMID 31103023, 2019). "Results of the present research clearly demonstrate that the PpiC recombinant protein efficiently stimulate cell-mediated immunity and results in significant opsonophagocytotic activity against E. faecalis ATCC 29212 infection." (PMID 31103023, 2019).
PPIC also shares sentences with these, for which no sentence is quoted: coronary artery disease (4 papers); dyslipidemia (3); hepatoma (3); Hypertension (3); cardiovascular diseases (1); diabetes (1); endothelial dysfunction (1); Hyperglycemia (1); ischemia (1); lung adenocarcinoma (1); lung carcinoma (1).